RAC3 (Rac family small GTPase 3)
Diseases named in the same sentence as RAC3 in open-access papers (continued):
Sharing a sentence is not in itself a finding about the gene and the disease.
Intellectual disability (5 papers, 2018 to 2023). "This analysis will be relevant also to the comprehension of the mechanisms underlying human intellectual disability that is caused by recently identified point mutations of the gene for Rac3." (PMID 31369617, 2019). "Misregulated RhoA, Rac1/Rac3 and cdc42 activity has been linked with intellectual disability (ID) and other neurodevelopmental conditions that comprise ID." (PMID 29925821, 2018). "A recent study describes the use of a genome-wide sequencing screen that has led to the identification of three de novo missense variants in the human gene for Rac3 that cause phenotypes of severe intellectual disability and brain malformations in the five patients carrying the mutations." (PMID 31514269, 2019). "This hypothesis is supported by recent findings that mutations in the Rac3 gene cause severe forms of intellectual disability in humans, as will be discussed in the next section." (PMID 31514269, 2019). "Additionally, although Rac3-KO mice show normal microscopic development of the brain, patients with RAC3 mutations (p.P29L and p.P34R in the switch I region and p.Q61L and p.E62K in the switch II region) reportedly exhibit severe intellectual disability and brain malformations." (PMID 37204479, 2023). "The importance of Rac3 for human health and its link to intellectual disability has been recently highlighted by the identification of mutations of the gene for Rac3 that cause neurodevelopmental defects in human patients." (PMID 31514269, 2019).
lung carcinoma (5 papers, 2018 to 2024). "In lung cancer, RAC3 accelerates cell proliferation by regulating cell cycle 39, and stimulates EMT and cell invasion through the p38 MAPK pathway." (PMID 37056933, 2023). "On the contrary, when RAC3 was overexpressed in lung cancer cells, the enhanced migration by CAFs was boosted." (PMID 37056933, 2023). "Among them, RAC3 is overexpressed and is involved in the initiation and progression of different types of cancers, including brain tumors, lung cancer, breast cancer, prostate cancer, esophageal cancer and ovarian cancer." (PMID 35847878, 2022). "PSD can increase lung cancer cell sensitivity to paclitaxel via inhibition of RAC3." (PMID 38200409, 2024). "Additionally, RAC3 was overexpressed in paclitaxel-resistant cells, and paclitaxel promoted RAC3 expression in paclitaxel-resistant lung cancer cells in a dose-dependent fashion." (PMID 38200409, 2024). "When RAC3 was knocked down in lung cancer cells, the enhanced migration by CAFs was diminished." (PMID 37056933, 2023). "Studies have suggested that knockdown RAC3 promotes apoptosis in lung cancer cells." (PMID 35847878, 2022). "Additionally, the silencing of RAC3 inhibits proliferation and induces apoptosis in human lung cancer cells." (PMID 30360391, 2018). "Moreover, we evaluated the clinical significance of RAC3 in lung cancer." (PMID 37056933, 2023). "The main limitation of this study is how RAC3 activates the PI3K/AKT signaling pathway, thereby increasing the sensitivity of lung cancer cells to paclitaxel." (PMID 38200409, 2024). "We found that PSD could only effectively inhibit cell proliferation in RAC3 overexpressing cells, indicating that PSD enhances the sensitivity of lung cancer cells to paclitaxel by inhibiting RAC3 expression." (PMID 38200409, 2024). "RAC3 level was higher in lung cancer specimens compared with the paired adjacent non-cancerous tissues." (PMID 37056933, 2023). "We further identified RAC3 as a downstream target of METTL3, and RAC3 facilitates NSCLC cell migration via the AKT/NF-κB pathway, suggesting that RAC3 m6A modification may serve as a potential therapeutic target for lung cancer treatment." (PMID 37056933, 2023). "However, it has not been evaluated whether RAC3 activates the AKT/NF-κB pathway in lung cancer cells." (PMID 37056933, 2023).
colorectal cancer (4 papers, 2014 to 2022). A primary or metastatic malignant neoplasm that affects the colon or rectum. "Although its probably association to cancer stem cells has not been previously investigated, in this work we demonstrated that RAC3 overexpression is mainly associated to a cancer stem marker enriched side population and is required to maintain some cancer stem properties of colorectal cancer cells." (PMID 29464039, 2018). "Taken together all these results, we may conclude that RAC3 overexpression is mainly associated to colorectal cancer stem cell markers, and contributes to maintain some cancer stem properties." (PMID 29464039, 2018). "RAC3 is a known high expression molecule in several types of tumors including colorectal cancer." (PMID 29464039, 2018). "Firstly, we investigated the RAC3 expression levels in patients with colorectal cancer (CRC)." (PMID 29209153, 2017). "In view of the results obtained in tumoral cells that naturally overexpress RAC3; we first investigated if RAC3 overexpression in non tumoral cells as a unique genetic introduced modification, is able to induce some of the tumoral properties that were observed in the human colorectal cancer cells." (PMID 29464039, 2018).
endometrial cancer (4 papers, 2023 to 2025). Primary or metastatic malignant neoplasm involving the endometrium (mucous membrane that lines the endometrial cavity). "For example, RAC3 is hypomethylated, thus inducing cell proliferation and invasion in endometrial cancer." (PMID 40123831, 2025). "Currently, many studies have shown that RAC3 may play a vital part in cell adhesion, migration, invasion, and apoptosis in different types of cancers, including breast and endometrial cancers, with anoikis being a crucial factor." (PMID 39659999, 2024).
epilepsy (4 papers, 2011 to 2023). A brain disorder characterized by episodes of abnormally increased neuronal discharge resulting in transient episodes of sensory or motor neurological dysfunction, or psychic dysfunction. "Mice with both Rac-N and Rac3 null mutations show defective migration and maturation of cortical and hippocampal inhibitory neurons, severe neurological and cognitive deficits, and spontaneous epilepsy, while the single disruption of Rac3 does not cause evident defects." (PMID 36568982, 2022).
esophageal cancer (4 papers, 2014 to 2023). A primary or metastatic malignant neoplasm involving the esophagus. "Rac3 supports Transforming Growth Factor (TGF)β1–induced E-cadherin down-regulation in esophageal cancer cells that is associated with poor prognosis in esophageal cancer." (PMID 31514269, 2019). "This is the first report to reveal that Rac3 is implicated in TGFβ1-induced E-cadherin down-regulation in esophageal cancer cells." (PMID 24684802, 2014). "This is the first evidence to support that Rac3 plays a critical role in the tumorgenesis of esophageal cancer and that FBXL19 exhibits an anti-tumor property by down-regulation of small GTPase." (PMID 24684802, 2014). "Further, we demonstrate that FBXL19 negatively regulates Rac3-mediated TGFβ1 signaling in esophageal cancer." (PMID 24684802, 2014). "This study is the first to report that Rac3 regulates TGFβ1-mediated E-cadherin down-regulation in esophageal cancer cells, indicating a critical role of Rac3 in the progress of esophageal cancer." (PMID 24684802, 2014). "Further, we found that Rac3 plays a critical role in TGFβ1-induced E-cadherin down-regulation in esophageal cancer cells." (PMID 24684802, 2014). "Here we investigate the role of FBXL19-mediated Rac3 degradation in TGFβ1-induced E-cadherin down-regulation in esophageal cancer cells." (PMID 24684802, 2014). "In this study, we show that Rac3 is strongly expressed in esophageal carcinoma cells and it regulates Snail expression." (PMID 24684802, 2014). "Additionally, FBXL19 targets lysine-166 of Rac family small GTPase 3 (RAC3) for proteasomal degradation to regulate TGFβ1-induced E-cadherin down-regulation in esophageal cancer cells." (PMID 32226545, 2020). "This study discovered that Rac3 plays an important role in the progress of esophageal cancer cells and the FBXL19 may function as a tumor suppressor through its ability to reduce Rac3 levels and inhibits TGFβ1 pathway." (PMID 24684802, 2014). "Inhibition of Rac3 by FBXL19 modulates E-cadherin expression in esophageal cancer cells." (PMID 24684802, 2014). "Future studies will be conducted to investigate the expression of Rac3 and FBXL19 in esophageal cancer tissues and adjacent normal tissues." (PMID 24684802, 2014). "However, the role of Rac3 in the pathogeneses of esophageal cancer has not been studied." (PMID 24684802, 2014).
brain tumors (3 papers, 2013 to 2024). "Analysis of the expression and mutation of the gene for Rac3 on a limited number of brain tumors has shown that the transcript for Rac3 is overexpressed in 19% of brain tumors (n = 26), while activating mutation occurs in 63% of brain tumors (n = 19)." (PMID 31514269, 2019).
melanoma (3 papers, 2017 to 2025). A malignant, usually aggressive tumor composed of atypical, neoplastic melanocytes. "SOCS3 and RAC3 displayed among the highest hypermethylation peaks in our aggressive melanoma lines (92 and 96%, respectively), with a very high differential methylation score, above 70%, between WM266-4 and WM115 cells." (PMID 36125262, 2022).
neuroblastoma (3 papers, 2018 to 2024). Neuroblastoma (NB) is the most common solid, extracranial childhood tumor. "Further, in a neuroblastoma cell line, Neurabin I was shown to directly interact with Rac3, an interaction that is required for Rac3 induction of neuritogenesis." (PMID 30265669, 2018). "In neuroblastoma N1E-115 cells, Rac1 and Rac3 appear to play opposite roles, since depletion of Rac1 leads to decreased focal adhesions and cell rounding, while depletion of Rac3 induces stronger adhesions and growth of neurite-like protrusions." (PMID 31514269, 2019).
non-small cell lung carcinoma (3 papers, 2023 to 2025). A group of at least three distinct histological types of lung cancer, including non-small cell squamous cell carcinoma, adenocarcinoma, and large cell carcinoma. "Similarly, CAFs secrete VEGFA to elevate METTL3 expression levels in non-small cell lung cancer cells, which subsequently facilitates m6A methylation of ras-related C3 botulinum toxin substrate 3 (RAC3) mRNA." (PMID 40986143, 2025). "First, CAFs can raise m6A activity inside tumor cells without necessarily transferring RNA: in non-small cell lung cancer (NSCLC), CAF-conditioned cues (notably VEGFA) induce tumor-intrinsic METTL3, elevating m6A on RAC3 and driving AKT/NF-κB signaling, invasion, and in vivo growth." (PMID 41280938, 2025).
polymicrogyria (3 papers, 2021 to 2025). A developmental brain abnormality characterized by an excessive amount of small convolutions on the surface of the brain and cognitive dysfunction. "In contrast, RAC3 variants have been demonstrated to impede neuronal migration and result in malformations of cerebral cortex, such as polymicrogyria and heterotopia." (PMID 40015633, 2025). "Cluster formation by mislocalized NeuN-positive neurons should account for the pathogenic mechanisms underlying the heterotopia and, partially, polymicrogyria and dysgyria, which represent the main neuronal migration/positioning abnormality observed in RAC3-related disorder." (PMID 35851598, 2022). "Resembling other RAC3-related disorder patients, polymicrogyria was an important finding in the prenatal NEDBAF case harboring the p.N92K variant, suggesting that this variant is linked to defective cortical neuron migration during corticogenesis." (PMID 40015633, 2025). "Collectively, these results suggest that RAC3-N92K impairs cortical neuron migration rather than merely delaying it, ultimately leading to heterotopia and/or polymicrogyria, commonly seen in patients with RAC3-related disorders." (PMID 40015633, 2025).
bladder tumor (2 papers, 2024). "Bladder tumors are among the most prevalent malignancies in the urinary system, and RAC3 has been linked to various types of cancer." (PMID 37728806, 2024). "This article seeks to explore the potential of RAC3 as both an early diagnostic marker for bladder tumors and a novel therapeutic target." (PMID 37728806, 2024). "In our study, we first derived that RAC3 was associated with bladder tumors by searching and analyzing the TCGA database." (PMID 37728806, 2024). "In conclusion, in this study, we found that RAC3 promotes the proliferation, differentiation, and invasion of bladder tumors, and its presence is associated with poor prognosis." (PMID 37728806, 2024). "This is the first report that RAC3 is highly expressed in serum and urine in addition to tumor tissue in patients with bladder tumors." (PMID 37728806, 2024). "In this study, the expression of RAC3 in serum and urine samples from patients with chronic cystitis and patients with different stages of bladder tumors was determined using the RAC3 ELISA kit." (PMID 37728806, 2024). "A study has shown that RAC3 is present in serum and urine samples of patients with chronic cystitis and bladder tumors, but the expression level is significantly higher in bladder tumors." (PMID 39659999, 2024). "Subsequently, we examined the correlation between RAC3 expression and the prognosis of bladder tumor patients." (PMID 37728806, 2024). "In the multivariate analysis, RAC3 expression, TNM stage, depth of infiltration, and degree of differentiation were identified as independent risk factors for bladder tumor prognosis." (PMID 37728806, 2024). "Subsequently, survival analysis by follow-up of bladder tumor patients revealed that bladder tumor patients with upregulated RAC3 expression had reduced overall survival." (PMID 37728806, 2024). "We observed that RAC3 expression was significantly higher in bladder tumor tissues compared to normal bladder tissues in individuals without bladder tumors." (PMID 37728806, 2024). "Subsequently, the correlation between the expression level of RAC3 and bladder tumors was investigated through multifactorial analysis and survival analysis." (PMID 37728806, 2024). "Based on our results, RAC3 shows promise as both a marker for early diagnosis of bladder tumors and a potential therapeutic target." (PMID 37728806, 2024). "The results showed that patients with bladder tumors had elevated levels of RAC3 expression in serum and urine compared to patients with chronic cystitis." (PMID 37728806, 2024). "The results revealed a positive correlation between RAC3 expression and bladder tumor grade and infiltration depth." (PMID 37728806, 2024). "The results showed that RAC3 was highly expressed in bladder tumor tissues and more significantly up-regulated in high-grade, invasive bladder tumor tissues." (PMID 37728806, 2024). "First, we compared the expression of RAC3 between normal bladder tissues and bladder tumor tissues at different stages and grades." (PMID 37728806, 2024). "Our results revealed a significant increase in the expression of RAC3 in serum and urine samples from patients with bladder tumors compared to those with chronic cystitis." (PMID 37728806, 2024). "We then detected the expression of RAC3 in bladder tumor tissues from patients with bladder tumors, normal tissues adjacent to cancer, and non-bladder tumor tissues in different individuals by immunohistochemical staining." (PMID 37728806, 2024). "To further validate this finding, we conducted an additional analysis using the GEPIA database and confirmed that RAC3 expression is upregulated in bladder tumor tissues compared to normal bladder tissue." (PMID 37728806, 2024). "As the study progressed, we further examined the expression of RAC3 in serum and urine samples from patients with chronic cystitis and bladder tumors." (PMID 37728806, 2024).
bladder tumor (continued). "Although the results of this study demonstrate the importance of RAC3 in bladder tumors, certain limitations remain." (PMID 37728806, 2024). "In our study, we utilized the UALCAN database to perform bioinformatics analysis, which revealed that RAC3 is among the genes that are overexpressed in bladder tumors." (PMID 37728806, 2024). "Importantly, high RAC3 expression emerged as an influential factor in the poor prognosis of bladder tumors, as patients with high RAC3 expression exhibited a lower overall survival rate than those with low RAC3 expression." (PMID 37728806, 2024). "Additionally, we compared the expression of RAC3 in the serum and urine of patients with bladder tumors and patients with chronic cystitis." (PMID 37728806, 2024). "Additionally, we identified a significant positive correlation between RAC3 expression levels and the stage, degree of differentiation, and infiltration of bladder tumors." (PMID 37728806, 2024). "In addition, the expression of RAC3 was more significantly upregulated in the serum and urine of patients with highly graded bladder tumors." (PMID 37728806, 2024). "Last, we investigated the potential of RAC3 as a biomarker for early diagnosis of bladder tumors." (PMID 37728806, 2024). "However, at present, there are few studies on the expression of RAC3 in bladder tumors, and most of them remain at the stage of bioinformatics analysis." (PMID 37728806, 2024). "Therefore, it is reasonable to believe that RAC3 has the promise to be a new therapeutic target for bladder tumors and even improve patient prognosis." (PMID 37728806, 2024). "Our findings revealed that RAC3 expression was upregulated in bladder tumor tissues." (PMID 37728806, 2024). "However, there is limited research on the relationship between Rac3 and bladder tumors, and further investigation is needed." (PMID 37728806, 2024). "Furthermore, we conducted an analysis to explore the differences in RAC3 expression in 30 bladder tumor tissues with varying grades and levels of tumor infiltration." (PMID 37728806, 2024). "In this study, we conducted several analyses related to RAC3 in bladder tumors." (PMID 37728806, 2024). "Therefore, we believe that RAC3 is expected to be a potential tumor marker for early diagnosis of bladder tumors." (PMID 37728806, 2024). "Therefore, it is particularly important to explore the clinical significance of RAC3 in patients with bladder tumors." (PMID 37728806, 2024). "Moreover, we observed higher levels of RAC3 expression in the serum and urine of patients with bladder tumors compared to those with non-bladder tumors." (PMID 37728806, 2024). "The univariate analysis demonstrated that RAC3 expression, tumor TNM stage, depth of infiltration, and degree of differentiation influenced the prognosis of bladder tumors." (PMID 37728806, 2024). "To validate our findings, we examined the expression of RAC3 in bladder tissues from 60 patients with bladder tumors and 10 patients without bladder tumors." (PMID 37728806, 2024). "The correlation between RAC3 expression and various clinicopathological characteristics, including gender, age, smoking history, TNM stage, degree of differentiation, and depth of infiltration, was examined in the 60 patients with bladder tumors." (PMID 37728806, 2024). "The expression of RAC3 was analyzed in bladder tumor tissues, adjacent non-tumor tissues, and normal bladder tissues using immunohistochemical staining." (PMID 37728806, 2024). "Furthermore, Kaplan–Meier analysis revealed that patients with RAC3-positive bladder tumors had a lower overall survival rate compared to those with negative RAC3 expression." (PMID 37728806, 2024). "Additionally, in a subset of 15 randomly selected patients with bladder tumors, we found high RAC3 expression in bladder tumor tissues compared to adjacent normal bladder tissues (taken as tissues 2 cm from the edge of the tumor)." (PMID 37728806, 2024).
bladder urothelial carcinoma (2 papers, 2020 to 2024). "Until now, the roles of PDGFRA, OLR1, RAC3, PDF, OAS1, and SH3BP2 in bladder urothelial carcinoma remain largely unexplored." (PMID 32733809, 2020).